CCL2 (C-C motif chemokine ligand 2)
Diseases named in the same sentence as CCL2 in open-access papers (continued):
Sharing a sentence is not in itself a finding about the gene and the disease.
pulpitis (10 papers, 2016 to 2024). Inflammation of the dental pulp. "The present results with β-CP also add to the growing literature implicating CCL2 in the development or maintenance of inflammatory pain, including orofacial pain associated with pulpitis." (PMID 37238715, 2023). "Accordingly, increased expression of CCL2 has been observed in chronic periapical lesions, indicating an association between chemokines and dental pulp inflammation." (PMID 33046027, 2020). "Our results demonstrated IL-6, TNF-α TNF, IL-1β, CXCL8 and CCL2 are closely related to the immune infiltrating cells in pulpitis." (PMID 37179325, 2023). "CCL2 has been reported to be increased in the tooth pulp following pulpitis, but we are unaware of any reports measuring CCL2 expression in the trigeminal ganglia in a rodent model of pulpitis." (PMID 37238715, 2023). "Surprisingly, we discovered that CCL2 inhibits cell autophagy and serves as a potential biomarker for pulpitis." (PMID 37208635, 2023). "In recent years, many studies have found that EZH2 can play important roles in various inflammatory diseases such as lupus-like diseases, dental pulp inflammation, and neuropathic pain by promoting the expression of macrophage chemokine CCL2." (PMID 34899918, 2021). "IL-6, TNF-α, IL-1, CXCL8, and CCL2 may be essential molecule of the immune response regulation network in pulpitis." (PMID 37179325, 2023). "In dental pulp inflammation, HDPCs express chemokines including CCL2, which could be induced by LPS or TNF-α stimulation." (PMID 34899918, 2021). "EZH2 might activate the macrophage chemotaxis and affect the transcription of anti-inflammatory factors via regulating the expression of CCL2 in the process of dental pulp inflammation." (PMID 34899918, 2021). "Therefore, IL-6, TNF-α, IL-1β, CXCL8, and CCL2 may participate in the occurrence and development of pulpitis by regulating the corresponding immune cells, which needs further experimental verification." (PMID 37179325, 2023). "In experimentally induced rat pulpitis, the kinetics of CXCL1 (GROa), CXCL2 (GROb), and CCL2 (MCP1) mRNA expression correlates with the infiltration of neutrophils, and CCL5 (RANTES) mRNA expression correlates with the infiltration of macrophages." (PMID 39917698, 2024). "Gene expression profiles and bioinformatics analysis confirmed that M0 macrophages and neutrophils play an irreplaceable role in pulpitis immunity, and the critical genes in the immune reaction to pulpitis are suggested to be IL-6, TNF-α, IL-1β, CXCL8, and CCL2." (PMID 37179325, 2023). "In addition to investigating the possible regulatory mechanisms of DEGs, we screened key genes as biomarker candidates for the diagnosis of pulpitis, including PTPRC, CD86, CCL2, IL6, TLR8, MMP9, CXCL8 and ICAM1." (PMID 33046027, 2020).
Shock (10 papers, 2007 to 2025). The state in which profound and widespread reduction of effective tissue perfusion leads first to reversible, and then if prolonged, to irreversible cellular injury. "Functional immune assays with patient Peripheral Blood Mononuclear Cells (PBMCs) revealed that burn shock patients (≥15% TBSA) produced elevated levels of MCP-1/CCL2 after innate immune stimulation ex vivo relative to mild burn patients." (PMID 28886135, 2017).
cerebral aneurysms (9 papers, 2012 to 2024). "Animal studies indicate two chemokines—C-X-C motif chemokine–ligand–8 (CXCL8/IL-8) and monocyte chemoattractant protein-1 (CCL2/MCP-1)—especially important in the formation and rupture of cerebral aneurysms." (PMID 32517149, 2020).
colon adenocarcinoma (9 papers, 2005 to 2023). "For example, recent study found increased expression of CCL2 mRNA in human gallbladder adenocarcinoma than those in human chronic cholecystitis; Exogenous CCL2 expression by murine colon adenocarcinoma cells have been found to promote its lung metastases through promoting neovascularization." (PMID 27145753, 2016). "Of all of the studied MCP chemokines, the expression of CCL2 in Caco-2 cells was the highest, while its levels were barely detectable in HCT 116, corroborating the notion of undetectable chemokine expression in another colon adenocarcinoma cell line, LS174T." (PMID 34885960, 2021). "To determine whether the impact of CCL2/12 blockade is applicable to additional tumors, we used another mouse model of MPE formation by MC38 colon adenocarcinoma in C57BL/6 mice." (PMID 23967166, 2013).
HCMV infection (9 papers, 2014 to 2025). "Our results have determined the roles played by IL-8 and CCL2 in the pathophysiology of HTMCs following HCMV infections." (PMID 40353220, 2025). "Our results showed that HCMV infection activated interferon signaling and significantly increased the expression of IL-8 and CCL2." (PMID 40353220, 2025). "Our findings demonstrated that HCMV infection of HTMCs leads to a significant increase in the expression of IL-8 and CCL2 at both the mRNA and protein levels." (PMID 40353220, 2025). "In particular, HCMV infection led mainly to the over-expression of CCL2, CCL3, CCL11, CXCR4, IL-1β, IL13, MMP1, MMP3, MMP9 and MMP13, SERPINA1, TNFα, and BMP7, and the gradual and constant downregulation of IL13RA2 (up to almost 800-fold at 14 days p.i.)." (PMID 32899126, 2020). "CCR2 and its ligand CCL2 are required for the mobilization of monocytes from the bone marrow and recruitment to the skin during murine cytomegalovirus infection and after exposure to ultraviolet light or chemical irritants." (PMID 25474197, 2014). "Importantly, HCMV infection of the TMCs has been shown to upregulate IL-8 and CCL2 which then alters the cytoskeletal dynamics and increases the outflow resistance resulting in an elevation of the IOP." (PMID 40353220, 2025). "However, our study provides important information on how TMCs behave after HCMV infection and the possible roles of IL-8 and CCL2." (PMID 40353220, 2025). "The research team also observed that infection with HCMV can promote the expression of two factors that increase HCMV infection and replication (CC-motif chemokine ligand 2 (CCL2/MCP-1) and CCR2, a CCL2-specific receptor)." (PMID 35336999, 2022). "We have previously shown that experimental latent HCMV infection of CD34+ progenitor cells alters the cellular secretome resulting in the upregulation of chemokines CCL8, CCL2 and secretion of TGF-β and cellular IL-10 (cIL-10)." (PMID 33912186, 2021).
hematoma (9 papers, 2014 to 2026). A hematoma is a collection of blood from a vascular structure into an extravascular space. "At early times, CCL2/CCR2 deficiency might decrease hematoma size but delay long-term recovery." (PMID 36704330, 2022). "CCL2/CCR2 deficiency might decrease hematoma size at early time points but delay the recovery." (PMID 36704330, 2022). "Our analysis indicated that VEGF, PDGF-BB, TNF-alpha, MMP-9, IL-6, CCL2, IL-1 alpha, MMP-1, MMP-8, and IL-8 were DEGs between the hematoma fluid and the peripheral blood before surgery." (PMID 35207175, 2022). "Clinical studies have reported associations between serum inflammatory markers in the acute phase of ICH, mainly CCL2, CXCL10, IL-6, IL-11, CRP, fibrinogen, and CSF cytokines with hematoma expansion and early neurological decline." (PMID 34439789, 2021). "In our study, neutrophils infiltrated into brain and promoted the mRNA transcription of CCL2 (also referred to as MCP-1), ICAM-1 and pro-inflammatory factors around hematoma." (PMID 30631264, 2018). "The IL-6 and CXCL8 in blood samples and CCL2, IL-5 and IL-13 in hematoma samples did not have significant standardized loadings, and were therefore excluded from the statistical models." (PMID 24587250, 2014).
hemorrhage (9 papers, 2011 to 2025). Loss of blood from the vascular compartment to the exterior or into nonvascular body space as a result of rupture or severance of the blood vessels. "As such, the CPXV infection model of hemorrhagic smallpox provides an opportunity to evaluate the effectiveness of immunomodulators targeting CCL2 and other pro-inflammatory mediators during progression of viral-induced hemorrhagic diseases." (PMID 34452435, 2021).
HIV encephalitis (9 papers, 2011 to 2025). "A polymorphism in CCL2 (a major CCR2 ligand) leading to increased chemokine expression was associated with AIDS dementia." (PMID 24359430, 2013). "In addition, CCL2 has been found to play a role in cancer, angiogenesis, bone remodeling, and HIV encephalitis, in which a common underlying pathogenic factor is CCL2-driven immune cell recruitment." (PMID 23102113, 2012). "Having been investigated extensively in the context of HIV encephalitis, CCL2 has until now been shown to recruit mostly monocytes and microglia at inflammatory sites in the CNS." (PMID 23102113, 2012). "Our results indicate that Ccl2 levels were increased to a greater extent (3- to 5-fold) in the brain of the SS+L and LL+L groups of HIV-1Tg rats versus the F344 rats, corroborating the role of upregulation of Ccl2 and its implications on HIV encephalopathy." (PMID 22216977, 2012).
invasive ductal carcinoma (9 papers, 2015 to 2025). "The findings also suggested that CCL2 expression in the tumor parenchyma is correlated with the histological grade of ductal invasive breast carcinoma." (PMID 37208442, 2023). "Through analysis of patient derived breast tissues and mouse models of DCIS, we showed that expression of CCL2, CCR2, phospho-SMAD3 and phospho-p42/44MAPK proteins were associated with invasive breast ductal carcinomas." (PMID 33888841, 2021). "Immunohistochemical analysis of CCL2 expression from 27 breast invasive ductal carcinoma specimens showed that CCL2 expression in tumor parenchyma significantly correlated with the histological grade of ductal infiltrative breast cancer." (PMID 33297571, 2020). "Also, TNF leads to the secretion of CCL-2 by mesenchymal stem/stromal cells (MSCs) in invasive ductal carcinoma, and this was related to an important migration of monocytic cells." (PMID 40362499, 2025). "Moreover, several studies have shown a positive correlation between the number of infiltrating macrophages in invasive ductal carcinoma and the expression of CCL2, CSF-1, and CCL5." (PMID 28881599, 2017). "In relation with this last comment, in previous studies conducted in our laboratory, we have observed that tumor cells of BCPs (invasive ductal carcinoma, stage I/II) produce bone marrow-MSCs chemotactic substances, such as IL-6, SDF-1, and CCL-2, among others." (PMID 37719885, 2023).
leishmaniasis (9 papers, 2012 to 2025). Infectious disease that is transmitted through the bite of hematophagous female phlebotomine sand flies. "Finally, serum levels of IFN-γ, TNF, CCL2, IL-12p70, IL-6, and IL-10 mediator previously implicated in the progression of leishmaniasis were measured using flow cytometry with the Mouse Inflammation CBA kit." (PMID 41259559, 2025). "Thus, the Th1 response is fundamental in the control of leishmaniasis and is responsible for the activation of macrophages in skin lesions, along with CCL2, reducing the parasitic load." (PMID 34253188, 2021). "The role of CC-chemokines CCL2, CCL3 and CCL5 in leishmaniasis has been tested in a number of studies." (PMID 22679519, 2012). "Additional chemokines, including the monocyte chemoattractant protein-1 (MCP-1/CCL2) and macrophage inflammatory protein 1a (MIP-1a/CCL3), have been proposed as potential immunotherapeutic agents for leishmaniasis, although current studies have only focused on their use in the treatment of VL." (PMID 39460345, 2024). "It has been proposed that in leishmaniasis, chemokines CCL2, CCL4, and CCL5 generally play a role not only as chemotactic factors but also as co-activators of macrophages and consequently have a part in the elimination of parasites." (PMID 22506080, 2012).
leukocytosis (9 papers, 2016 to 2022). "One LD50 injection in mice produced a severe envenomation state, with a significant reduction of the complement activity, leukocytosis, neutrophilia, monocytosis, and strong systemic production of IL-6, CCL2, and TNF-α." (PMID 33936074, 2021). "In the blood, we observed leukocytosis and increased amounts of the chemokines CCL2 and CCL7, as well as of GCSF; in addition, serum IgEs were elevated in Δ/Δep2 mice." (PMID 27431613, 2016).
meningioma (9 papers, 2020 to 2025). A generally slow growing tumor attached to the dura mater. "The levels of the cytokines IL-6, IL-10, and GM-CSF, as well as the levels of the chemokine CCL2, were analyzed in the plasma of 27 patients with meningiomas (since one case had an undetermined subtype)." (PMID 38259646, 2023). "A correlation between macrophage infiltration and the expression of the monocyte chemoattractant protein-1 (MCP-1/CCL2) by meningiomas has been demonstrated, suggesting a role for this chemokine in the mechanism of meningioma infiltration by TAMs." (PMID 36768342, 2023). "Additionally, we investigated the presence of miR-21 and the different cytokines: Interleukin-6 and Interleukin-10 (IL-6 and IL-10), Granulocyte-Macrophage Colony-Stimulating Factor (GM-CSF) and Chemokine (C-C motif) Ligand 2 (CCL2) in the plasma of 28 patients diagnosed with meningioma." (PMID 38259646, 2023). "Similarly, CCL2, a monocyte chemoattractant, was found to be highly expressed in meningioma tissue." (PMID 35712492, 2022).
nasopharyngeal carcinoma (9 papers, 2016 to 2023). A carcinoma arising from the nasopharyngeal epithelium. "For example, high serum CCL2 is associated with increased metastasis and poor overall survival in nasopharyngeal carcinoma." (PMID 30158126, 2018). "Recently, palmitate and TNF-α were shown to synergistically promote CCL2 production in monocytes, and CCL2 was demonstrated to drive radioresistance, metastasis, and epithelial–mesenchymal transition in nasopharyngeal carcinoma." (PMID 31847240, 2019). "In a nasopharyngeal carcinoma (NPC) model, CCL2 correlated with radioresistance and metastasis." (PMID 35365161, 2022).
Salmonella Infections (9 papers, 2004 to 2024). Infections with bacteria of the genus SALMONELLA. "ELISA and flow cytometry analysis of serum and PBMC for Ccl2 (monocyte chemoattractant protein-1) levels, a key cytokine in the murine response to Salmonella infection, indicated significant increases suggesting an appropriate immune response." (PMID 38521952, 2024). "When comparing these findings to the effects of Salmonella infection on motility and invasion, we discovered that Salmonella infection induces a similar promotion of motility and invasion as CCL2." (PMID 38528181, 2024). "(C–E) RT-qPCR analysis of mRNAs encoding inflammatory cytokines (Tnfα, Il1β, and Il6), chemokines (Ccr2, Ccl2, Cxcl1, and Cxcl10) and macrophage biomarkers (Nos2 and Arg1) in BMDMs measured at the indicated times after Salmonella infection (multiplicity of infection [MOI] = 1) (n = 5)." (PMID 39475776, 2024).
abdominal aortic aneurysm (8 papers, 2013 to 2026). Enlargement and ballooning of the vessel that supplies arterial blood to the abdomen, pelvis and legs. "The CCR2/CCL2 molecular axis is a critical mediator of abdominal aortic aneurysm (AAA) pathogenesis." (PMID 41783018, 2026).
acute lymphoblastic leukemia (8 papers, 2012 to 2026). Leukemia with an acute onset, characterized by the presence of lymphoblasts in the bone marrow and the peripheral blood. "Also, CCL2, ICAM1 and VCAM1 have a positive effect on MSCs adhesiveness, survival and proliferation in patients with acute lymphoblastic leukaemia." (PMID 29495420, 2018). "Also, CCL2 and IL-8 have a positive impact on MSC survival, proliferation and adhesiveness to acute lymphoblastic leukemia (ALL) cells." (PMID 22296115, 2012).
alcohol use disorder (8 papers, 2016 to 2025). "We previously demonstrated that ethanol induced the expression of CCL2 in animal models of FASD as well as adult models of alcohol use disorder." (PMID 37008214, 2023). "While their study found significantly higher CCL2 concentrations in end-stage ALD compared to controls, the results are not directly comparable to ours, as their control group consisted of individuals who were 10 years younger and had a history of alcohol abuse." (PMID 40731922, 2025).
alcoholic hepatitis (8 papers, 2007 to 2025). Acute hepatitis resulting from ingestion of alcohol. "This contrasts with previous studies reporting elevated CCL2 levels in conditions like alcoholic hepatitis and fibrosis associated with primary biliary cholangitis." (PMID 40731922, 2025). "In contrast to human data where Ccl2, Ccl3, Ccl20 and Cxcl10 transcripts were significantly changed in alcoholic hepatitis compared to healthy control, none of these statistically significant changes were found in the murine models." (PMID 32051453, 2020).
aortic aneurysm (8 papers, 2014 to 2025). A ruptured aneurysm located in the wall of the proximal portion of the descending aorta proceeding from the arch of the aorta. "Furthermore, the relative mRNA level of inflammatory factors of aortic aneurysm was examined by quantitative PCR, which suggested minoxidil significantly upregulated the expression levels of IFN-γ, NOS2, and CCL2." (PMID 37383707, 2023).
Atrophy (8 papers, 2017 to 2026). Any weakening or degeneration, especially through lack of use. "The expression of monocyte chemoattractant protein 1 (MCP-1/CCL2) was found to be associated with thymic atrophy and the neutralization of CCL2 via an anti-CCL2 pAb enhanced antileukemic T-cell response and increased the survival of AML mice." (PMID 36814919, 2023). "For example, in chronic renal allograft injury resulting in progressive interstitial fibrosis, early urinary CCL2 is an independent predictor for the subsequent development of interstitial fibrosis and tubular atrophy at 24 months." (PMID 33519923, 2020). "Previous studies have reported that the CCL2−/− model demonstrates confluent areas of visible atrophy after 16 months of age34; therefore, no changes were expected to be seen at this point." (PMID 29354704, 2017).
cardiac arrest (8 papers, 2009 to 2025). Cessation of breathing and/or cardiac function. "The converse was observed in the case of the chemokine MCP-1 (CCL2), which was highly expressed in the skin of “cardiac arrest group” animals, but expressed at far lower levels in the skin of the “injury group” animals." (PMID 26635801, 2015).
cerebral malaria (8 papers, 2011 to 2024). A sequestration of Plasmodium falciparum in the brain, which can cause coma and/or seizures. "However, future analysis is necessary to confirm or investigate this hypothesis, mainly by evaluating the production levels of CCL2, CCL4, CXCL4, CXCL8, CXCL10, and the receptors CXCR3 and CCR2, correlated with susceptibility to cerebral malaria and lung inflammation." (PMID 38256880, 2023).
diabetic cardiomyopathy (8 papers, 2012 to 2025). Diabetic cardiomyopathy is a disorder of the heart muscle in people with diabetes. "In diabetic cardiomyopathy (DCM), both serum CCL2 and myocardial CCL2 mRNA levels are elevated." (PMID 39850880, 2024).